OPA1 (OPA1 mitochondrial dynamin like GTPase)
Diseases named in the same sentence as OPA1 in open-access papers (continued):
Sharing a sentence is not in itself a finding about the gene and the disease.
Cerebral ischemia (11 papers, 2014 to 2025). Restriction of arterial blood supply to the brain associated with insufficient oxygenation to support the metabolic requirements of the tissue. "The protection afforded by OPA1 from heart and brain ischemia corroborates early findings that implicated OPA1 and OPA1-dependent cristae remodeling in cell death." (PMID 26039448, 2015). "Studies have revealed that MT activates mitochondrial fusion and suppresses fission through the AMP-activated protein kinase (AMPK)-OPA1 axis, thereby mitigating myocardial and cerebral ischemia-reperfusion injury as well as vascular calcification." (PMID 41422263, 2025). "Immunofluorescence results showed that the expression levels of Mfn1, Mfn2, and OPA1 were downregulated in mouse cerebral cortex after cerebral ischemia–reperfusion, while 14, 15‐EET treatment reversed this protein downregulation." (PMID 37017405, 2023). "Our study showed that the expression levels of MFN1, MFN2, and OPA1 protein were downregulated after cerebral ischemia–reperfusion, and 14, 15‐EET treatment inhibited the downregulation of these proteins and promoted mitochondrial fusion." (PMID 37017405, 2023). "Mild overexpression of OPA1 prevented muscular atrophy, heart and brain ischemia, and liver apoptosis by OPA1-dependent mitochondrial cristae remodeling." (PMID 31551424, 2019). "In conclusion, exercise pretreatment may promote mitochondrial fusion via the up-regulation of OPA1, and this may provide the basis of neuroprotective function for against cerebral ischemia and reperfusion injury." (PMID 24633199, 2014). "Indeed, overexpression of OPA1 protects from heart and brain ischemia and from ROS production." (PMID 34679654, 2021). "Cerebral ischemia–reperfusion induces mitochondrial dynamics disorders, upregulates the expression of the mitochondrial division protein Fis 1, and inhibits the expression of mitochondrial fusion proteins MFN1, MFN2, and OPA1, while 14, 15‐EET treatment reverses this process." (PMID 37017405, 2023). "In parallel relative to DG, OPA1 expression significantly (p < 0.05) decreased in CA1 after global cerebral ischemia in mice treated with post-injury MM-control, while mice treated with anti-miR-200c demonstrated significantly (p < 0.05) preserved CA1 OPA1 expression." (PMID 36466801, 2022).
dilated cardiomyopathy (11 papers, 2017 to 2023). Cardiomyopathy which is characterized by dilation and contractile dysfunction of the left and right ventricles. "Specific ablation of cardiac Yme1L in mice to activate OMA1 accelerates OPA1 proteolysis, triggering mitochondrial fragmentation and altering cardiometabolic, leading to dilated cardiomyopathy." (PMID 37603376, 2023). "It has also been shown that OPA1-mediated mitochondrial fragmentation triggers dilated cardiomyopathy and HF in mice; Mitochondrial autophagy is an important mediator of mitochondrial quality control in cardiomyocytes." (PMID 36330217, 2022). "Mfn1/Mfn2 deficient mice and Tmem135 TG mice show cardiac hypertrophy while mice with induced processing of OPA1 develop dilated cardiomyopathy." (PMID 30102730, 2018).
Insulin resistance (11 papers, 2018 to 2025). Increased resistance towards insulin, that is, diminished effectiveness of insulin in reducing blood glucose levels. "Lastly, although OPA1 protein expression was unaltered, insulin resistance has previously been associated with altered mitochondrial dynamics." (PMID 39057712, 2024). "Diabetic cardiomyopathy is marked by reduced expression of fusion proteins (Mfn1, Mfn2, OPA1), increased fission, and overproduction of reactive oxygen species (ROS), which contribute to insulin resistance and cardiac dysfunction." (PMID 41000071, 2025). "To assess insulin resistance in WT and OPA1+/− mice, we measured plasma insulin concentrations and calculated the Homeostatic Model Assessment of Insulin Resistance (HOMA-IR) before and after HFD exposure." (PMID 40722980, 2025). "We also reported that HFD consumption for 11 weeks in both OPA1+/− and WT mice induced signs of peripheral insulin resistance, as shown by a significant increase in HOMA-IR relative to the same animals tested earlier (i.e., before or after 6 weeks of HFD exposure)." (PMID 40722980, 2025). "Importantly, simultaneous deletion of Fgf21 and Gdf15 in BAT significantly attenuated the resistance to DIO and insulin resistance in OPA1 BKO mice." (PMID 40897647, 2025). "Notably, combined Fgf21 and Gdf15 deletion in OPA1 BKO significantly blunted the resistance to DIO and insulin resistance observed in OPA1 BKO mice." (PMID 40897647, 2025). "Overall, our results indicate that 11 weeks of a HFD impaired glucose tolerance associated with insulin resistance and that the genetic inactivation of OPA1 slightly decreased fasting insulinemia, but no other metabolic parameters." (PMID 40722980, 2025). "Moreover, Opa1 levels decreased with the progression of insulin resistance." (PMID 35334815, 2022). "Our study shows a significant reduction in Opa1 and Mfn2 expression in the skeletal muscle, and this could be responsible for the abnormal mitochondrial structure and could potentially contribute to insulin resistance." (PMID 35334815, 2022). "To assess glucose homeostasis and insulin resistance in mice fed HFD, we first used a new cohort of OPA1 BKO mice to recapitulate our previous findings." (PMID 40897647, 2025).
lung adenocarcinoma (11 papers, 2018 to 2025). A carcinoma that arises from the lung and is characterized by the presence of malignant glandular epithelial cells. "In KRas-mutant lung adenocarcinoma, OPA1 plays critical roles in mitochondrial respiration and NAD + regeneration through regulating cristae morphology." (PMID 41146909, 2025). "OPA1 participates in resistance against the tyrosine kinase inhibitor gefitinib in lung adenocarcinoma, the Bcl-2 antagonist Venetoclax in acute myeloid leukemias, and in the development of residual disease following standard-of-care treatment for TNBC." (PMID 40691145, 2025). "OPA1 (Optic Atrophy Protein 1), a mitochondria-shaping protein, participates in resistance against gefitinib in a lung adenocarcinoma cell line and cisplatin in NSCLC." (PMID 39681067, 2024). "Unfortunately, our attempts to identify the upstream regulators that alter the expression of Opa1 in this lung adenocarcinoma cell line were unsuccessful." (PMID 37019897, 2023). "Our studies nominate the mitochondria-shaping protein Opa1 as a promising target to overcome gefitinib resistance in lung adenocarcinoma." (PMID 37019897, 2023). "Here we show that the mitochondria-shaping protein Opa1 participates in resistance against the tyrosine kinase inhibitor gefitinib in a lung adenocarcinoma cell line." (PMID 37019897, 2023). "Here we show that in vitro and in vivo growth of KRas-driven lung adenocarcinoma is unaffected by deletion of Drp1 but is inhibited by deletion of Opa1, the GTPase that regulates inner membrane fusion and proper cristae morphology." (PMID 36516772, 2022). "Lung adenocarcinoma cells with an overexpression of OPA1 was positively correlated to cisplatin resistance while OPA1 downregulation induced the mitochondrial cristae deformation, thus increasing the release of cytochrome c and triggering apoptosis." (PMID 32974209, 2020). "Similarly, OPA1 targeting increases gefitinib-induced cell death in lung adenocarcinoma and sorafenib-induced apoptosis in liver cancer." (PMID 41146909, 2025). "In addition, in hepatocellular carcinoma (HCC) and lung adenocarcinoma, OPA1 expression determines the response to chemotherapeutics, and OPA1 knockdown sensitizes cells to the treatment." (PMID 37627290, 2023). "For example, Opa1 is required for cancer angiogenesis, is upregulated in Cisplatin resistant lung adenocarcinomas, in Venetoclax-resistant acute myeloid leukemia cells, and in triple-negative breast cancer (TNBC), the growth of which is curtailed by genetic and pharmacological Opa1 inhibition." (PMID 37019897, 2023). "Besides, OPA1 overexpression displays more resistance to cisplatin treatment in lung adenocarcinoma cells, whereas OPA1 downregulation promotes the release of cytochrome c, thus inducing apoptosis and attenuating the cisplatin resistance." (PMID 32974209, 2020). "OPA1 is overexpressed and has poor prognosis value in lung adenocarcinoma cells." (PMID 29459674, 2018). "Therefore, multiple yet uncharacterized pathways may be involved in the upregulation of Opa1 in gefitinib-resistant lung adenocarcinoma cells." (PMID 37019897, 2023).
melanoma (11 papers, 2017 to 2025). A malignant, usually aggressive tumor composed of atypical, neoplastic melanocytes. "The raw RNA sequencing data of DNML1, MFN1, and OPA1 from normal and melanoma samples, associated with NRAS-type mutations, were analyzed from a previous study." (PMID 40141318, 2025). "As such, lower levels of DDR1, MFN2 and OPA1 and higher levels of pAMPK and higher amoeboid scores were also found at the IF of human melanoma metastatic lesions." (PMID 37217519, 2023). "Since DEA depolarized the ΔΨm, it seems logical that the DEA-induced mitochondrial fragmentation was caused by inhibiting fusion that was supported by the release of OPA1 in the case of B16F10 melanoma previously." (PMID 35163464, 2022). "We found that the levels of Mfn1 and Mfn2 and Opa1 protein were considerably reduced in cryptolepine treated melanoma cells." (PMID 28473727, 2017). "Accordingly, melanoma cells at the IF of human primary tumours showed lower levels of DDR1, MFN2 and OPA1, while harbouring higher levels of pAMPK and higher amoeboid score." (PMID 37217519, 2023).
cardiac hypertrophy (10 papers, 2017 to 2025). "Studies have found that OPA1 is acetylated in the states of cardiac hypertrophy and SIRT3 deficiency." (PMID 34660720, 2021). "The results of Co-IP assays indicated that Tom70 could directly bind to Opa1 and that deficiency in mitochondrial Opa1 mimics the cellular features of pathological cardiac hypertrophy induced by Tom70 deficiency." (PMID 40978492, 2025). "In Drosophila and mice, inhibiting Opa1 expression may cause abnormal mitochondrial morphology and cardiac hypertrophy." (PMID 34660720, 2021). "Regardless, our results reveal an intriguing regulatory circuit linking Opa1 processing to cardiac hypertrophy and highlight the role of Oma1 as a stress-protective protease in heart disease." (PMID 39093974, 2024). "Our results highlight the critical regulatory role of Opa1 processing, mitochondrial dynamics, and metabolism for cardiac hypertrophy." (PMID 39093974, 2024). "However, whether H2S regulated DRP1 and OPA1 in the protective effect against myocardial hypertrophy was unknown." (PMID 30647820, 2018). "Thus, the requirement of Oma1-mediated Opa1 processing for cardiac hypertrophy is independent of mitochondrial stress signaling." (PMID 39093974, 2024). "We found that NaHS failed to enhance OPA1 expression and reduce DRP1 formation in ISO-administrated SIRT3 KO mice, which may be one of the reasons that NaHS failed to improve oxidative stress and myocardial hypertrophy after ISO administration in SIRT3 KO mice." (PMID 30647820, 2018).
cardiac ischemia (10 papers, 2016 to 2025). "In a mouse model of myocardial ischemia/reperfusion, melatonin regulated OPA1 by activating AMPK, thereby maintaining mitochondrial function and reducing myocardial cell death." (PMID 35265261, 2022). "To date, key questions still remain unanswered in better understanding the function of different Opa1 conformational states and its role in the context of cardiac ischemia." (PMID 35326125, 2022). "In murine hearts after myocardial ischemia and reperfusion injury, the expression of OPA1 is downregulated, with a consequent decline in cardiomyocyte survival and mitochondrial function." (PMID 35887048, 2022). "In contrast, OPA1 overexpressing mice show a reduction in heart and brain damage after cardiac ischemia and reperfusion." (PMID 35887048, 2022). "Mitochondrial fission is observed during myocardial ischemia, and mice partially deficient in the fusion protein OPA1 were shown to exhibit higher IRI, while mild Opa1 overexpression has previously been revealed to be protective." (PMID 33765018, 2021). "Moreover, increased mitochondrial fusion and mitophagy through the AMPK-OPA1 signaling pathway was observed to protect against cardiac ischemia/reperfusion injury, whereas OPA1 knockout abolished the protective effects." (PMID 35163080, 2022). "Reduced Opa1 expression inhibited mitophagy resulting in myocardial ischemia-reperfusion injury." (PMID 32155590, 2020). "Additionally, Opa1 upregulation reduced myocardial ischemia through activation of the Brain-derived neurotrophic factor (BDNF)/tropomyosin-related kinase B (TrkB) pathway." (PMID 32155590, 2020). "Considering that Hyp treatment in our study upregulated both Mfn1/Mfn2 and Opa1, it is conceivable that strategies aimed at activating mitofusins may complement Opa1-mediated inner membrane fusion to achieve more robust mitochondrial protection in the setting of cardiac ischemia–reperfusion injury." (PMID 40978492, 2025).
lung carcinoma (10 papers, 2018 to 2024). "ANXA2 interacted with T-cell immunoglobulin and mucin domain-containing molecule 4 (TIM-4) and mediated TIM-4-induced lung cancer progression by activating PI3K/AKT/OPA1 axis." (PMID 38688909, 2024). "Here, we identify high OPA1 as a gatekeeper for high mitochondrial fusion activity in CSCs of human lung cancer." (PMID 36809297, 2023). "This is consistent with previous findings of Opa1 upregulation in cisplatin-resistant lung cancer cells." (PMID 37019897, 2023). "Collectively, TIM-4 promotes oxidative phosphorylation of lung cancer cells to accelerate tumor progress via ANXA2/PI3K/AKT/OPA1 axis, which sheds significant new lights on the potential role of TIM-4 in regulating tumor cell metabolism." (PMID 36806050, 2023). "Collectively, OPA1 bridges lipogenesis and mitochondrial dynamics in CSCs, promoting mitochondrial fusion activity and stem-like properties of human lung cancer." (PMID 36809297, 2023). "Together, lipogenesis regulates mitochondrial dynamics via OPA1 for controlling CSCs in human lung cancer." (PMID 36809297, 2023). "We elucidated the molecular mechanism and roles of OPA1 promoting lung cancer through single-cell sequencing and molecular biological experiments." (PMID 36573240, 2022). "siRNA targeting OPA1 also reversed the promotion of OXPHOS by TIM-4 in lung cancer cells." (PMID 36806050, 2023). "As expected, siRNA targeting OPA1 also reversed the promotion of mitochondrial activity induced by TIM-4 overexpression in lung cancer cells, including the increase in mitochondrial membrane potential, and the differences in the numbers of damaged and healthy mitochondria." (PMID 36806050, 2023). "Here, we found that copy number amplification of OPA1 and MFN1 were co-occurring and synergistically activated in tumor epithelial cells in lung cancer tissues." (PMID 36573240, 2022). "In both in-vitro and in-vivo cases, western blot analysis indicated that FPS/siOPA1 had a higher silencing effect on OPA1 gene expression compared with other nanoparticles, and this makes FPS a potential therapeutic agent for treating lung cancer." (PMID 35507584, 2022). "Here, we found that copy number amplification of OPA1 and MFN1 were co-occurring and synergistically activated in lung cancer tissues." (PMID 36573240, 2022). "Additionally, research has shown concurrent amplification of OPA1 and MFN1 copy numbers, synergistically activated in tumor epithelial cells in lung cancer tissues." (PMID 38911373, 2024). "Thus, OPA1 is a gatekeeper that connects lipid metabolism and mitochondrial dynamics for CSC maintenance in human lung cancer." (PMID 36809297, 2023).
Stroke (10 papers, 2020 to 2025). Sudden impairment of blood flow to a part of the brain due to occlusion or rupture of an artery to the brain. "Data from various sources have shown that, after stroke, the expression of fusion-associated proteins, Mfns and OPA1, decreased and affected the mitochondrial fusion process." (PMID 35153669, 2021). "In the present study, we found that OPA1 expression was significantly suppressed in SH‐SY5Y cells after OGD/R by WB experiments, which demonstrated the importance of the AMPK‐OPA1 pathway in the pathogenesis of stroke." (PMID 40790939, 2025). "Ischemia disrupts the dynamic balance of fusion and fission in part by inhibiting expression of fusion proteins MFN2 and OPA1 and recent studies in experimental stroke suggests that inhibition of mitochondrial fission and promotion of fusion is protective." (PMID 36466801, 2022). "As a mitochondrial regulatory gene, OPA1 plays a dispensable role in the regulation of mitochondrial fission/fusion and other related functions, OPA1 as a talented therapeutic target for stroke prevention and treatment." (PMID 35040556, 2022). "At the time of stroke, rats treated with LV-UCP2 still showed a large UCP2 upregulation in the striatum, associated with increases in OPA1 and FIS1 protein levels, and reductions in PGC1-α, SOD2, TNFα mRNA levels and NRF2 protein levels." (PMID 32560241, 2020). "Importantly, it has been reported that the control of transgenic overexpression of OPA1 can “tighten” the cristae junction, limit the release of cytochrome c, and provide protection against ischemic brain injury after stroke." (PMID 35571256, 2022). "Furthermore, overexpression of OPA1 tightens and limits cytochrome c release, providing protection against the effects of ischemic brain injury after stroke." (PMID 36552630, 2022). "On this basis, we found that OPA1 expression was significantly suppressed in SH‐SY5Y cells after OGD/R by WB experiments, which demonstrated the importance of the AMPK‐OPA1 pathway in the pathogenesis of stroke." (PMID 40790939, 2025).
Atrophy (9 papers, 2010 to 2022). Any weakening or degeneration, especially through lack of use. "However, the mild overexpression of OPA1 attenuated heart I/R injury, denervation-induced muscular atrophy, and the susceptibility of Fas-induced liver injury through the resistance of mitochondrial apoptotic cristae remodeling." (PMID 36192726, 2022). "In contrast, the levels of OPA1 protein were not different between atrophy and non-atrophy groups, and neither exhibited a significant correlation with occupation ratios." (PMID 35173176, 2022).